AGRP (agouti related neuropeptide)
Description:
Signaling protein that functions as an antagonist of melanocyte-stimulating-hormone receptors MC3R and MC4R by precluding agonist-induced signaling, thereby inhibiting cAMP production within the hypothalamus and adrenal gland. Involved in the control of feeding behavior via the central melanocortin system. Has very low activity towards MC5R. Also promotes endocytosis of MC3R and MC4R in an arrestin-dependent mechanism.
Synonyms: AGRT; ART; ASIP2
Tractability: Antibody: UniProt places it where antibodies can reach, with high confidence; UniProt predicts a signal peptide or a membrane-spanning region; its Gene Ontology location is reachable by antibodies, with medium confidence.
Gene: Protein-coding gene on chromosome 16 (67,482,571 to 67,483,548, reverse strand). Ensembl gene ENSG00000159723.
Subcellular location: Secreted; Golgi apparatus lumen
Subcellular location (Human Protein Atlas): Vesicles; Predicted to be secreted
Pathways (Reactome):
Gene expression (Transcription): FOXO-mediated transcription of oxidative stress, metabolic and neuronal genes
Gene Ontology:
Molecular function: neuropeptide hormone activity; receptor antagonist activity; signaling receptor binding; type 1 melanocortin receptor binding
Biological process: negative regulation of adenylate cyclase-activating G protein-coupled receptor signaling pathway; neuropeptide signaling pathway; positive regulation of appetite; regulation of appetite; regulation of feeding behavior; adult feeding behavior; positive regulation of feeding behavior; circadian rhythm; eating behavior; hormone-mediated signaling pathway; long-day photoperiodism; maternal process involved in female pregnancy; response to insulin
Cellular component: extracellular region; Golgi lumen; neuronal cell body
Genetic constraint (gnomAD): Loss-of-function variants: 8 observed, 13.23 expected, observed/expected ratio (o/e) 0.6, 90% interval 0.35 to 1.09. The upper end of that interval is the gene's LOEUF score, 1.09, which puts it in group 4 of 6, group 1 being the genes least tolerant of losing a copy. Missense variants: 155 observed, 165.25 expected, observed/expected ratio (o/e) 0.94, 90% interval 0.82 to 1.07. Synonymous variants: 63 observed, 67.3 expected, observed/expected ratio (o/e) 0.94, 90% interval 0.76 to 1.15.
Homologues: Orthologues: chimpanzee AGRP (100% identical), macaque AGRP (95% identical), dog AGRP (82% identical), guinea pig AGRP (82% identical), rabbit AGRP (81% identical), mouse Agrp (80% identical), pig AGRP (78% identical), rat Agrp (73% identical), tropical clawed frog agrp (40% identical), zebrafish agrp (31% identical). Paralogues in human: ASIP (26% identical).
Diseases named in the same sentence as AGRP in open-access papers:
AGRP is named in the same sentence as 85 diseases in open-access papers, as found by Europe PMC text mining. Sharing a sentence is not in itself a finding about the gene and the disease. The quoted sentences say what the papers report.
Obesity (204 papers, 2009 to 2026). Accumulation of substantial excess body fat. "AGRP has been shown to stimulate appetite, diminish energy expenditure, and contribute to obesity, while also elevating the risk of adverse cardiovascular outcomes in the context of AMI." (PMID 40242450, 2025). "Together these findings demonstrate that the specific loss of miR-33 in AgRP neurons is sufficient to promote obesity and metabolic dysfunction in mice fed a HFD, similar to what was observed with global miR-33 deficiency." (PMID 38459068, 2024). "The role of these populations in leptin signalling has also been evaluated and, whereas a knockout of the LepR in AGRP/NPY neurons of adult mice causes extreme obesity, deletion of the LepR from adult POMC neurons has only a minimal effect." (PMID 39478220, 2024). "Here, the authors show that miR-33, represses the activity of AgRP neurons, and selective loss of miR-33 in AgRP neurons promotes obesity and metabolic dysfunction in mice." (PMID 38459068, 2024). "In this work we demonstrate that selective loss of miR-33 in AgRP neurons is sufficient to increase feeding in HFD fed mice leading to the development of obesity and metabolic dysfunction." (PMID 38459068, 2024). "AgRP neurons drive hunger, and excessive nutrient intake is the primary driver of obesity and associated metabolic disorders." (PMID 38459068, 2024). "Utilizing unique mouse models, we demonstrate that miR-33 plays a critical role in the regulation of AgRP neurons, and that loss of miR-33 leads to increased feeding, obesity, and metabolic dysfunction in mice." (PMID 38459068, 2024). "Human mutations in the MC4R trigger obesity, and AgRP neurons are the natural antagonist of these receptors favoring increased food intake." (PMID 37082122, 2023). "We found that PrlhNTS neuron activation and Prlh overexpression in PrlhNTS cells abrogates AgRP neuron-driven hyperphagia and ameliorates the obesity of mice deficient in melanocortin signaling or leptin." (PMID 34462445, 2021). "Ablation of OGT in AgRP neurons causes white adipose tissue browning and confers protection from diet-induced obesity." (PMID 33460647, 2021). "We set out to characterize how the regulation of AgRP neurons is modulated by diet-induced obesity and subsequent weight loss." (PMID 32720646, 2020). "AgRP polymorphisms have been associated with diet, leanness, obesity, type-2 diabetes and anorexia nervosa." (PMID 31804567, 2019). "Obesity is also associated with ghrelin resistance in NPY/AgRP neurons in the ARC leading to reduced ghrelin- and fasting-induced appetite response." (PMID 29433631, 2018). "This led to the identification of the endogenous melanocortin antagonist AgRP, whose transgenic overexpression in brain also causes obesity." (PMID 30177968, 2018). "The associations between α-MSH and AgRP levels and anthropometric and nutritional markers of malnutrition and obesity were also assessed." (PMID 26758700, 2016). "Polymorphisms in the AGRP (16q22) locus have been linked with anorexia nervosa, furthermore in cognitive functioning there, and to late onset obesity in its rs11575892 T allele." (PMID 27147943, 2016). "Polymorphism in the gene encoding AgRP is associated with the development of both anorexia nervosa and obesity." (PMID 26758700, 2016). "Central injection of the AgRP peptide promotes feeding and chronic overexpression of AgRP causes obesity." (PMID 26300745, 2015). "ChR2 mediated-stimulation of AgRP neurons causes immediate feeding, while hM3Dq-mediated stimulation of AgRP neurons causes robust feeding over hours and an obesity phenotype when applied over several days." (PMID 26300745, 2015). "Genetic disruption of AMPK specifically in POMC or AgRP neurons causes obesity or resistance to obesity, respectively, while the neurons themselves maintain the ability to respond to insulin and leptin but not glucose." (PMID 23550218, 2013).
Obesity (continued). "The results indicate that heparanase inhibits obesity by degrading HS chains, presumably linked to syndecan-3, thereby suppressing the binding of AgRP to MC4R." (PMID 22479599, 2012). "It has been shown previously that adult lesion of AgRP neurons produces a starvation phenotype, which is averted in the setting of leptin-deficient obesity." (PMID 23028821, 2012). "Recent research has demonstrated that long-term activation of ARC AgRP neurons or hypothalamic GABAergic neurons, by specific expression of the Na+ channel NachBac, induces severe obesity and hyperphagia, akin to the phenotypes of leptin-deficient (ob/ob) mice." (PMID 40130157, 2025). "Additionally, several proteins were linked to metabolic disorders such as obesity, diabetes, and hyperuricemia, including AGRP, LEP, SORT1 and SOD2." (PMID 40242450, 2025). "While activating ARC AgRP/NPY neurons has been shown to be both aversive and rewarding depending on the duration of activation, the positive valence associated with inhibiting ARC AgRP/NPY neurons lends itself well to targeting these neurons for obesity drug development." (PMID 39644359, 2025). "Finally, deleting leptin receptors in BNC2 neurons caused marked hyperphagia and obesity, similar to that observed in a leptin receptor knockout in AGRP neurons." (PMID 39478220, 2024). "The altered physical interactions of astrocytes-AgRP/Npy neurons together with expanded AgRP/Npy populations in male offspring under maternal HFD programming might be important in increasing their susceptibility for developing obesity at adulthood." (PMID 38493217, 2024). "Moreover, specific restoration of leptin receptors in POMC neurons (presumed activation of these neurons) or AgRP neurons (presumed inhibition of these neurons) causes little effects on obesity reversal in db/db mice." (PMID 37069175, 2023). "Recently, AGRP neurons have been identified as the primary target of leptin action in a seminal study demonstrating that AGRP neuron–specific Lepr deletion at the adult stage in mice causes severe hyperphagia, obesity, and diabetes." (PMID 36189793, 2022). "Given that CRISPR-mediated deletion of Lepr in adult AGRP neurons causes hyperphagia, obesity, and diabetes, we hypothesized that TET3 might affect leptin signaling in AGRP neurons." (PMID 36189793, 2022). "Importantly, selective deletion of SK3 from ARH Agouti-related peptide (AgRP) neurons increases firing frequency of AgRP neurons and sensitivity to diet-induced obesity in mice, and this is associated with chronic hyperphagia and decreased energy expenditure." (PMID 36210455, 2022). "Since obesity in DicerCKO mice is associated with the loss of the Dicer1 gene both in AgRP and POMC neurons, while miR-15-5p is highly expressed in POMCCre-GFP neurons, we sought to genetically inactivate this microRNA in POMCCre-Cas9-GFP cells during adulthood." (PMID 35873003, 2022). "Similarly, mice exhibiting AgRP/NPY-specific TCPTP deficiency are resistant to diet-induced obesity and exhibit increased energy expenditure." (PMID 34502119, 2021). "Conclusively, we reveal a critical role of tanycyte insulin receptors in gating feeding-state-dependent regulation of AgRP neurons and systemic insulin sensitivity, and show that insulin resistance in tanycytes contributes to the pleiotropic manifestations of obesity-associated insulin resistance." (PMID 34931084, 2021). "Thus, enhancing Prlh-mediated neurotransmission by the NTS blocks the hyperphagia and obesity associated with leptin deficiency, increased AgRP neuron activity and/or impaired melanocortin signaling, as well as during DIO." (PMID 34462445, 2021). "Thus, obesity causes persistent resistance to two key gastrointestinal signals at the level of AgRP neuron activity, and this is associated with decreased ability of these hormones to modulate food intake." (PMID 32720646, 2020).
Obesity (continued). "However, abolishing OGT in AgRP neurons blocks excitation of AgRP neurons, promoting browning of white adipose tissue and thus protecting the mutated mice against diet-induced obesity and insulin resistance." (PMID 33139642, 2020). "Moreover, both conventional and AgRP-restricted P2Y6-deficient animals exhibit reduced obesity as well as improved whole-body insulin sensitivity when exposed to long-term HFD feeding." (PMID 29619754, 2018). "In this study, we generated conditional Sirt1 KI mouse models and asked whether conditional Sirt1 overexpression in mouse POMC or AgRP neurons prevents age-associated weight gain and diet-induced obesity." (PMID 24374551, 2014). "In the current study we tested whether conditional Sirt1 overexpression in mouse POMC or AgRP neurons prevents age-associated weight gain and diet-induced obesity." (PMID 24374551, 2014). "This phenotype may be surprising, given that disruption of leptin receptor expression specifically in AgRP neurons results in mild obesity, suggesting that loss of leptin action via PI3K signaling might result in a similar phenotype." (PMID 19883613, 2009). "Moreover, reduced RQ and enhanced VO2 were associated with protection from high fat diet-induced obesity, glucose intolerance and diabetes in mice with ablated agouti-related protein (AgRP) producing neurons and in retinaldehyde dehydrogenase 1a1 knock-out mice." (PMID 23248643, 2012). "Obesity also attenuates the rapid responses of AgRP neurons to sensory food cues and food consumption." (PMID 40502019, 2025). "Recent research using CRISPR/Cas9 technology to inactivate the LEPR gene in AgRP neurons of adult mice led to severe obesity and glucose metabolism disorders." (PMID 40452923, 2025). "Overexpressing AgRP [Tg(b-actin: AgRP)] in zebrafish has resulted in the development of a genetic model of obesity." (PMID 41134486, 2025). "We analyzed metabolic indicators and observed that, under NCD feeding, AgRP-Raf1-OE mice exhibited significant weight gain, increased food intake, and notable increases in fat mass, as well as other obesity-related phenotypes." (PMID 40432214, 2025). "Here, we show that iron overload-induced ROS activate hypothalamic FoxO1, increasing AgRP expression and promoting age-dependent obesity, revealing a central role for this pathway in energy balance." (PMID 41037185, 2025). "Identifying non-AgRP neuronal subsets that are responsible for hyperphagia and obesity — but are insufficient to drive hyperglycemia — in leptin-deficient states is a priority for future research." (PMID 40371641, 2025). "Collectively, our findings demonstrate that fat sensory cues during development are sufficient to mimic the deleterious effects of HFD-induced obesity on AgRP neurons and resulting metabolic alterations." (PMID 41326798, 2025). "Conversely, Raf1 knockout in AgRP neurons protected against diet-induced obesity, reducing fat mass and improving glucose tolerance." (PMID 40432214, 2025). "In obesity, appetite regulation is disrupted, and asprosin has been shown to increase appetite through the activation of AgRP neurons." (PMID 41211169, 2025). "In summary, AgRP neurons play a crucial role in regulating feeding, weight, and energy metabolism and are significant for understanding metabolic diseases such as obesity and diabetes." (PMID 40452923, 2025). "In this study, we found that the expression of RAF1 was significantly increased in hypothalamic AgRP neurons of diet-induced obesity (DIO) mice." (PMID 40432214, 2025). "Hypothalamic iron accumulation promotes age-dependent obesity by increasing mitochondrial ROS and driving FoxO1 nuclear translocation, which upregulates AgRP expression and disrupts energy homeostasis." (PMID 41037185, 2025). "Conversely, knocking out the OGT gene in AgRP neurons reduces their excitability, promotes browning of white adipose tissue, and mitigates diet-induced obesity and insulin resistance." (PMID 40130157, 2025).
Obesity (continued). "Our findings highlight the importance of age-related hypothalamic iron dysregulation in obesity pathogenesis and elucidate the impact of oxidative stress on AgRP neuronal function." (PMID 41037185, 2025). "Under normal chow diet feeding, overexpression of Raf1 in AgRP neurons led to obesity in mice characterized by increased body weight, fat mass, and impaired glucose tolerance." (PMID 40432214, 2025). "Maternal caloric restriction during pregnancy blunts the leptin neonatal surge, which impairs axon development from ARC POMC and AGRP/NPY neurons and leads to adulthood outcomes linked to vulnerability to obesity." (PMID 40474775, 2025). "By activating hypothalamic Agouti-related peptide (AgRP) neurons in mice to simulate obesity’s effects, we observed changes in the small noncoding RNA payload of sperm." (PMID 40021730, 2025). "Reducing hypothalamic iron via intranasal iron chelator DFP suppressed AgRP expression, increased energy expenditure, and improved obesity." (PMID 41037185, 2025). "We conclude that in diabetic male Lepob/ob mice, AgRP neuron hyperactivity is required for hyperglycemia but is dispensable for obesity." (PMID 40371641, 2025). "The role of GIP signaling in glucose-mediated AgRP neuron inhibition is consistent with the anorexigenic effects and obesity treatment efficacy of GIPR agonists." (PMID 40857106, 2025). "We conclude from these findings that AgRP neuron hyperactivity is required for the hyperglycemia of diabetic Lepob/ob mice but is dispensable for their hyperphagia and obesity." (PMID 40371641, 2025). "Overall, these findings indicate that elevated expression of Raf1 in AgRP neurons in HFD-fed mice results in a mild increase in obesity and related metabolic disorders." (PMID 40432214, 2025). "Further, we have recently documented that CRISPR-mediated, agouti-related protein (AgRP) neuron-specific Tet3 ablation induces hyperphagia, systemic insulin resistance, obesity and type 2 diabetes." (PMID 38216792, 2024). "Mice lacking AgRP presented an important reduction in feeding, whereas those with increased expression of AgRP developed hyperphagia and obesity." (PMID 39876968, 2024). "We further show that chemogenetic over-activation of AgRP neurons in the hypothalamus, as present in obesity, significantly impairs glucose tolerance that is completely normalized by acute BCAA reduction." (PMID 38844453, 2024). "Collectively, these data reveal that p62 acts on POMC or AgRP neurons to promote POMC expression, but inhibits AgRP expression to regulate energy metabolism and prevent obesity." (PMID 39479445, 2024). "In a high-fat diet (HFD)-induced obesity model, we determined the gene expression levels of agouti-related peptide (AgRP) and pro-opiomelanocortin (POMC) in the hypothalamus." (PMID 39057086, 2024). "HFD-induced obesity also affects the metabolic signalling-dependent interplay created by the opposite neuronal regulation of AgRP and POMC neurocircuits." (PMID 38378998, 2024). "The “POMC, alpha-MSH, and AGRP in the regulation of food intake and energy expenditure in obesity in the hypothalamus” pathway map (pathway #149; FDR 1.118e-2; 13 modulated network objects out of 43) is highlighted for significant modulation." (PMID 39109301, 2024). "Altogether, these data suggest that PVH neurocircuits are less impacted by HFD-induced obesity in contrast with the effect of HFD on the coordinated interaction between AgRP and POMC neurocircuits." (PMID 38378998, 2024). "Activation of AgRP leads to the development of obesity, not only through hyperphagia, but also via reduction in voluntary exercise." (PMID 36817590, 2023). "High fat feeding-induced obesity affects the NPY/AgRP co-expressing neurons in the arcuate nucleus via cytokines that promote hypothalamic inflammation and astrocytosis." (PMID 37571301, 2023). "We found that the LepR in AgRP neurons plays a pivotal role in the control of obesity and glucose homeostasis." (PMID 37043384, 2023).